APP (amyloid beta precursor protein)
Diseases named in the same sentence as APP in open-access papers (continued):
Sharing a sentence is not in itself a finding about the gene and the disease.
Hypertension (21 papers, 2009 to 2025). The presence of chronic increased pressure in the systemic arterial system. "We investigate these effects in an AD (PS1/APP) rat model (FAD+) with coexisting hypertension-associated small vessel disease (SVD), as well as in their transgene-negative littermates (FAD-)." (PMID 40890882, 2025). "In a study focusing on the genotypic distributions of these APP variants in the Chinese population, patients with the CC genotype of rs2211772, had a decreased risk of hypertension compared to those with TT or TC at the same locus." (PMID 39766777, 2024). "The same study also considered the effect of the methylation of the APP gene and noted that methylation levels at different CpG sites also correlated with differential hypertension risk." (PMID 39766777, 2024). "In this work, the polymorphism and methylation of the APP gene, closely related to AD, were associated with hypertension." (PMID 36941702, 2023). "Nonetheless, reports on the association of APP gene polymorphism and promoter methylation with hypertension are limited." (PMID 36941702, 2023). "Nonetheless, studies on the association of APP gene polymorphism and promoter methylation with hypertension are limited." (PMID 36941702, 2023). "CAA is histopathologically characterized by the deposition of Aβ, which is another cleavage product of APP and represents a cerebral vessel disorder known as the 2nd most frequent cause of hemorrhage in the elderly brain after hypertension-related bleedings." (PMID 30413735, 2018). "In addition to its prevalent association with AD, different genotypes in variants within APP have also been observed to associate with differential hypertension risk." (PMID 39766777, 2024). "Previous research findings have also pointed out that hypertension promotes APP processing, which may be a mechanism of pathogenic interaction between hypertension and AD." (PMID 36941702, 2023). "Thus, our case–control study for the first time explored the relationship between APP gene SNP mutation and hypertension." (PMID 36941702, 2023). "Amyloid precursor protein (APP) mutations are implicated in hypertension development." (PMID 36941702, 2023). "This is similar to hypertension only rabbits, and could indicate synergism of the two risk factors in affecting the expression of molecules related to APP." (PMID 23874591, 2013). "Hypertension in APP/PS1 mice accelerates progression of AD-like pathologies, including cognitive dysfunction and amyloid pathology, in addition to reduced density of microvessels and cerebrovascular dysfunction." (PMID 31708792, 2019). "Our results showed that BD-lesions consist of N-terminal APP-fragments and were associated with the severity of CAA and with myocardial fibrosis in individuals with arterial hypertension." (PMID 30413735, 2018). "Since APP is involved in both CAA and BD a molecular link appears possible as well as a link with hypertension-associated cardiomyocyte alterations." (PMID 30413735, 2018). "Despite early hypertension, APP/PS1 mice showed only sporadic hypoperfusion." (PMID 40141679, 2025). "This may be attributed to changes in methylation levels, which trigger changes in the sequence of transcription factor binding sites, hence affecting APP gene expression and abnormal metabolism of APP, ultimately resulting in hypertension." (PMID 36941702, 2023). "Vascular risk factors such as aging and hypertension can alter APP homeostasis in cerebrovascular tissue not only by modulating APP expression and processing but also by affecting APP protein interaction network." (PMID 32973564, 2020). "That is, the high pulse pressures generated within the larger vessels in the milieu of hypertension, if transmitted to the microvascular beds as increased microvascular stretch, could act as a mechanical switch for the endothelium to overexpress APP and favour APP cleavage into Aβ." (PMID 29374229, 2018).
Hypertension (continued). "The common area between the hypertension only- and hypercholesterolemia plus sham groups showed up-regulated focus genes related to UBC, APP, SERPINB2, TNF and HNF4A, and down-regulated focus genes related to UBC." (PMID 23874591, 2013). "However, synergism between effects of hypertension and AD on APP processing as a primary mechanism, is not supported by the subtle differences in Aβ observed in our model and in human MxD data." (PMID 31708792, 2019).
glioblastoma (20 papers, 2009 to 2026). The most malignant astrocytic tumor (WHO grade IV). "H4SW cells are a stable cell line whereby the amyloid precursor protein (APP) Swedish mutation was introduced into a human glioblastoma cell line." (PMID 33815510, 2021). "Herein, we investigated the APP-mediated alteration of HMOX1 expression and related epigenetic regulation mechanisms using glioblastoma cells harboring a Swedish mutation of APP." (PMID 27058954, 2016). "Increased amyloid precursor protein (APP), including both mRNA and protein expression, has been linked to glioblastoma (GBM) yet the physiological effects are poorly understood." (PMID 41003874, 2025). "Overall, OLFML2A was shown to primarily regulate glioblastoma through Wnt/β-catenin signaling by targeting APP." (PMID 34650914, 2021). "To ascertain ApoE allelic form and A03 effects on sAPPα in vitro, we used transiently-transfected human glioblastoma cells because they express human APP and enzymes." (PMID 30514854, 2018). "It has been reported that combined stimulation of IL-1β, IL-6, and IFN-γ in U373 glioblastoma cell lines and primary human astrocytes could induce APP production and lead to increased Aβ levels." (PMID 39626951, 2024). "We aim to elucidate the distribution pattern of IDO-1+ macrophages/microglia in the human brain tissues, human glioblastoma, APP/PS1 mouse brains, and quinolinic acid model brains and explore the physiological and immunological roles of IDO-1+ macrophages/microglia." (PMID 34735466, 2021). "In glioblastoma multiforme (GBM), APP has been shown to directly bind to the CD74 receptor on the surface of TAMs and suppress their phagocytic function." (PMID 41561750, 2025). "APP is overexpressed with APLP in multiple cancers, including glioblastoma and breast, pancreatic, lung, colon, and prostate cancer, which is known to participate in the progression, proliferation, and migration of cancer cells." (PMID 38728235, 2024). "We found that other human brain cell lines such as glioblastoma (U87) and microglia (CHME3) also express high levels of APP compared with primary normal human dermal fibroblasts (NHDFs) or 293T cells." (PMID 29142315, 2017). "Förster resonance energy transfer (FRET) -based techniques have recently been applied to study the interactions between β-site APP-cleaving enzyme-GFP (BACE1-GFP) and amyloid precursor protein-mRFP (APP-mRFP) in U373 glioblastoma cells." (PMID 23443094, 2012). "However, APP is highly expressed in brain and other organs and is overexpressed with APLP in multiple cancers, including glioblastoma and breast, pancreatic, lung, colon, and prostate cancer." (PMID 34066808, 2021). "In addition, it has been reported that APP may be related to the malignant progression of human astrocytic tumors, and it has been shown that intra-tumoral injection of Aβ potently inhibits the angiogenesis of human glioblastoma and thus inhibits the growth of the tumor." (PMID 19480719, 2009).
memory (20 papers, 2014 to 2025). The activities involved in the mental information processing system that receives (registers), modifies, stores, and retrieves informational stimuli. "It has been shown that crude extracts of H. perforatum can reduce the memory impairment in amyloid precursor protein (APP)‐transgenic mice." (PMID 31037808, 2019). "In order to investigate how Aβ contributes to AD pathology, several AD transgenic models, such as APP/PS1 and J20, were developed overexpressing Aβ precursor protein (APP) and displaying early memory deficits." (PMID 37626593, 2023). "In APP/PS1 double Tg mice, the EGFR antagonist gefitinib improves memory impairments." (PMID 39434878, 2024). "In animal models, using an amyloid precursor protein (APP)/presenilin-1 (PS-1) double transgenic (TG) mouse model of AD, treatment with QUET attenuated memory impairment, decreased the number of β-amyloid (Aβ) plaques and up-regulated the cerebral anti-apoptosis B-cell lymphoma (Bcl)-2 protein." (PMID 37511284, 2023). "Given the effects of post-torpor arousal on synaptic plasticity and memory, we next tested whether torpor also rescues memory deficits in an APP/PS1 mouse model of AD, which shows decreased synaptic plasticity and a memory impairment at 6 months of age25,26." (PMID 34326412, 2021).
proteinopathy (20 papers, 2014 to 2024). "Although our studies focused on models for controlling expression of pathogenic APP, we anticipate that the approaches taken and lessons learned will be applicable to many other proteinopathies." (PMID 35394029, 2022). "Like HD, AD is also viewed as a proteinopathy, since it is associated with accumulation of amyloid fibrils derived from the Amyloid Precursor Protein (APP)." (PMID 33465062, 2021). "The interaction of DDX49 with proteins known to be involved in neurological disorders such as Huntingtin-associated protein 1 (HAP1) and Amyloid-beta protein APP suggests that DDX49 might also have a role in diverse proteinopathies." (PMID 29618122, 2018). "Furthermore, pathological impairment of lipid microenvironment may also affect membrane partitioning of other raft-associated proteins involved in distinct proteinopathies, such as glutamatergic receptors, PrPc and APP." (PMID 31068782, 2019). "We have recently validated the utility of [18F]ROStrace in multiple models of proteinopathy, including the APP/PS1 AD model and the A53T model of synucleinopathy." (PMID 39456479, 2024). "Given the significance of neuronal activity in impacting proteinopathy, a recent study demonstrates that APP transgenic mice exhibit reduced neuronal activity in thalamic reticular nucleus (TRN) bringing about increased sleep fragmentation and reduced SWS in comparison to non-transgenic littermates." (PMID 37085942, 2023). "While familial AD has essentially genetic causes expressed in amyloid precursor protein (APP) and presenilin leading early in life to specific proteinopathies and inducing neurodegenerative pathologies, these mechanisms are less consistent in the sporadic AD of elderly subjects." (PMID 37004127, 2023). "To test if MSUT2 can regulate other forms of proteinopathy besides tau pathology, we crossbred MSUT2 KO mice with 5xFAD mice, which develop human-like Aβ plaques due to overexpression of mutant APP and PS1 genes." (PMID 38472475, 2024). "Both events have also been predicted for the APP/PS1 model of AD, and surely would have enormous consequences for AD proteinopathy." (PMID 34830060, 2021). "Importantly, a similar approach has been successfully applied to other proteinopathy-related proteins, including TDP-43 and amyloid precursor protein (APP)." (PMID 35263320, 2022).
brain injury (19 papers, 2013 to 2025). Acute and chronic (see also brain INJURIES, CHRONIC) injuries to the brain, including the cerebral hemispheres, CEREBELLUM, and brain STEM. "Brain trauma causes the upregulation of amyloid precursor protein (APP), resulting in the accumulation of APP in injured axons, which is cleaved abnormally to the amyloid-beta (Aβ) protein." (PMID 34768742, 2021). "Currently, the earliest reported time at which axonal injury can be detected in post-mortem traumatic brain injury (TBI) tissue by βAPP (Beta Amyloid Precursor Protein) immunohistochemistry is 35 min." (PMID 35488928, 2022). "Based on these TBI injury models, it was proposed that the APP protein expression upregulation in the nerve terminals following brain injury has an important function in adaptive and neuroprotective responses." (PMID 34476545, 2021). "BACE1 cleaves a variety of substrates and is associated with decreased dendritic spine integrity and axonal blebbing, which is due to an increase in the number of APP positive neuronal terminals after brain trauma." (PMID 33071724, 2020). "Studies have shown that after EPA treatment of APP/PS1 mice with traumatic brain injury (TBI), the load of A beta in the brain (especially in the hippocampus) was significantly reduced compared to untreated mice." (PMID 31485251, 2019). "Here the effects of severe penetrating TBI on APP and tau cleavage processing were investigated in a rodent model of penetrating ballistic-like brain injury (PBBI)." (PMID 27428544, 2016). "In the present study, we have used the entorhinal denervation model, a classical model of structural reorganization after brain trauma, to better understand the role of APP and APP processing in denervated areas of the brain following injury." (PMID 24404197, 2014). "APP represents a widely used marker for the detection of axonal pathology e.g., in the analysis of traumatic brain injury (TBI), which has also been previously used to detect axonal degeneration in APP/PS1KIho mice." (PMID 25018730, 2014). "For experimental concussion in swine performed with the same biomechanical loading conditions of head rotational acceleration, female brains displayed a greater extent of APP accumulation in swollen axonal profiles and more widespread loss of Nav1.6 along injured axons than observed for males." (PMID 38705966, 2024). "Furthermore, SHD promotes the level of IL-6 and APP proteins in rats after ischemic brain injury and reduces the level of AKT1 and VEGFA proteins." (PMID 35097126, 2022). "This aspect of brain trauma may be similar to the observation that APP and its fragments are detectable in the soma, as well as dendritic and axonal terminals of injured cells." (PMID 33071724, 2020). "Furthermore, APP is expressed and cleaved dramatically in CNS injuries, such as spinal cord or traumatic brain injuries." (PMID 24358169, 2013). "Elevations in CSF biomarkers, APP and tau in particular, may suggest recent or ongoing neurological injury, for example axonal stretch-related injury or synaptic disruption, as has been proposed in traumatic brain injury and other conditions." (PMID 28212403, 2017). "Aβ protein is derived from the cleavage of a transmembrane protein, amyloid precursor protein (APP), of which function has been related to a neuroprotective effect against traumatic brain injury." (PMID 30533568, 2018). "Indeed, different animal models of acute hypoxia-ischemia, traumatic brain injury (TBI) and excitotoxicity have revealed protective effects of APP or APPsα." (PMID 28210211, 2017).
ischemia (19 papers, 2010 to 2025). A hypoperfusion of the BLOOD through an organ or tissue caused by a PATHOLOGIC CONSTRICTION or obstruction of its BLOOD VESSELS, or an absence of BLOOD CIRCULATION. "However, the molecular mechanisms underlying regulation of LTCC by APP, the function in healthy neurons and the role in ischemia and degeneration remain elusive." (PMID 28210211, 2017). "The tests performed on gerbils showed the connection between increased accumulation of APP in neurons and their exposure to ischemia." (PMID 35268287, 2022). "The effect of ischemia on caveolin-1 levels and co-immunoprecipitation of caveolin-1 with N- or C-terminal fragments of the APP (N-APP and C-APP) and ADAM10 was also investigated." (PMID 36289917, 2022). "The identified miRNA was further verified by the OGD test to restore neuronal changes after ischemia through APP." (PMID 34413720, 2021). "APP expression is upregulated under conditions of metabolic stress, ischemia, brain injury and inflammation." (PMID 28210211, 2017). "In this review article, we present convergent evidence from human studies, animal models and in vitro experiments for a neuroprotective role of APP in ischemia, brain injury and neurodegeneration." (PMID 28210211, 2017). "This suggests that ischemia influences APP metabolism probably through inhibition of fast axonal transport of APP." (PMID 20673341, 2010). "The cleavage of APP in endothelial cells, macrophages, platelets, and neurons may be influenced by factors such as aging, ischemia, and inflammation." (PMID 38398429, 2024). "Testing the efficacy of APP96-110 in other neuronal injury models such as spinal cord injury and ischemia, where APP expression has been shown to be altered, could broaden the therapeutic utility of APP9-110." (PMID 29320530, 2018). "Furthermore, APP and its cleaved products have been shown to be upregulated both in neurons and glial cells, in response to injury, including ischemia and various other brain injury models, supporting a role of APP as a stress response protein." (PMID 26447481, 2015). "Alternatively, ischemia may have an effect on earlier stages, e.g. reduce APP gene expression, but observations in experimental ischemia suggest that this is less likely." (PMID 20673341, 2010). "Thus, the balance of caveolin-1 during ischemia may affect APP processing and the degree of damage to brain cells after ischemia." (PMID 36289917, 2022). "Interestingly, previous evidence showed that APP and/or Aβ accumulation was increased in rodents after inducing ischemia, which may imply a possible compensation effect of APP/Aβ from brain damage." (PMID 33014535, 2020). "There were 10 active constituents against ICVD, including quercetin, luteolin, kaempferol, and naringenin, and 10 important targets for anticerebral ischemia, namely, PIK3CA, APP, PIK3R1, MAPK1, MAPK3, AKT1, PRKCD, Fyn, RAC1, and NF-κB1." (PMID 35432563, 2022). "GFAP-positive reactive astrogliosis were observed not only in APP transgenic mice but also in other animal models such as doxycycline inducible astrocytic MAO-B transgenic mice, ischemia models, LPS-injected animals, tau transgenic mice, and APP knock-in mice." (PMID 35210989, 2022). "Meanwhile, we found that MANF is mostly expressed in neurons in the brains of APP/PS1 mice, which is in accordance with the characteristics of MANF expression in rat ischemia model." (PMID 30760285, 2019). "To determine whether APP−/− and/or its cleavage products are an integral part of a metabolic stress response, we subjected APP−/− mice to a bilateral common carotid artery occlusion resulting in global ischemia." (PMID 22912719, 2012).